Y_RNA (Y RNA )
Gene: Miscellaneous RNA gene on chromosome 12 (93,460,725 to 93,460,826, reverse strand). Ensembl gene ENSG00000200011.
Homologues: Orthologues: chimpanzee Y_RNA (99% identical), macaque Y_RNA (96% identical), pig Y_RNA (76% identical). Paralogues in human: Y_RNA (91% identical), RNY3 (90% identical), Y_RNA (90% identical), Y_RNA (89% identical), Y_RNA (88% identical), RNY3P1 (87% identical), Y_RNA (87% identical), RNY3P16 (86% identical), Y_RNA (86% identical), Y_RNA (85% identical), RNY3P14 (84% identical), RNY3P2 (84% identical), and 97 more.